OR11H4 (olfactory receptor family 11 subfamily H member 4)
Description:
Odorant receptor.
Synonyms: OR14-36
Gene: Protein-coding gene on chromosome 14 (20,239,286 to 20,244,349, forward strand). Ensembl gene ENSG00000176198.
Subcellular location: Cell membrane
Pathways (Reactome):
Sensory Perception: Expression and translocation of olfactory receptors; Olfactory Signaling Pathway
Genetic constraint (gnomAD): Loss-of-function variants: 1 observed, 1.48 expected, observed/expected ratio (o/e) 0.68, 90% interval 0.21 to 1.84. That is too few expected variants to judge how well the gene tolerates losing a copy. Missense variants: 460 observed, 392.12 expected, observed/expected ratio (o/e) 1.17, 90% interval 1.09 to 1.27. Synonymous variants: 162 observed, 151.35 expected, observed/expected ratio (o/e) 1.07, 90% interval 0.94 to 1.22.
Homologues: Orthologues: chimpanzee OR11H4 (98% identical), mouse Or11h4 (89% identical), dog OR11H4 (88% identical), pig OR11H4 (87% identical), mouse Or11h4b (87% identical), rat Olr1633 (87% identical), rabbit OR11H4 (85% identical), guinea pig OR11H4 (84% identical), rat Or11h4c (83% identical). Paralogues in human: OR11H7 (68% identical), OR11H6 (67% identical), OR11H2 (62% identical), OR11H12 (62% identical), OR11H1 (61% identical), OR11G2 (60% identical), OR11A1 (45% identical), OR9G1 (40% identical), OR10X1 (38% identical), OR9A4 (37% identical), OR9A2 (37% identical), OR9A1P (36% identical), and 21 more.
Diseases named in the same sentence as OR11H4 in open-access papers:
OR11H4 is named in the same sentence as 1 disease in open-access papers, as found by Europe PMC text mining. Sharing a sentence is not in itself a finding about the gene and the disease. The quoted sentences say what the papers report.
cancer (1 paper, 2023). A tumor composed of atypical neoplastic, often pleomorphic cells that invade other tissues. "We suggest that OR11H4 is a novel marker predicting the outcome of patients with stage 2 or 3 CRC and may be a target of potent immunotherapies targeting cancer-initiating cells." (PMID 36222933, 2023).